PPARG (peroxisome proliferator activated receptor gamma)
Diseases named in the same sentence as PPARG in open-access papers (continued):
Sharing a sentence is not in itself a finding about the gene and the disease.
Obesity (continued). "Interestingly, RXR and PPARγ antagonism was reported to ameliorate high-fat diet (HFD)-induced obesity and IR through reduction of triacylglycerol (TAG) in WAT, skeletal muscle, and liver in KKAy mice (a genetic model for obesity-diabetes syndrome) in contrast with untreated mice." (PMID 33926085, 2021). "Background and purpose: Obesity is becoming a major global health issue and is mainly induced by the accumulation of adipose tissues mediated by adipogenesis, which is reported to be regulated by peroxisome proliferator-activated receptor γ (PPARγ) and CCAAT enhancer-binding protein α (C/EBPα)." (PMID 34232916, 2021). "Thus, PPARγ agonists have been applied to control insulin resistance induced by obesity." (PMID 34444660, 2021). "Therefore, additional research is required to fill knowledge gaps and determine whether the activated PPARγ pathway induces autophagy or vice versa during obesity." (PMID 32015340, 2020). "Furthermore, in vivo studies revealed that supplementation of NAC in murine models that were fed a high fat diet to induce obesity, reduced triglyceride and cholesterol content within the liver by reducing PPARγ levels amongst other genes involved in hepatic storage and metabolism of lipids." (PMID 32903449, 2020). "Interestingly, Biocarta also found significant overrepresentation in two well-known anti-inflammatory pathways: the PPARγ-related obesity pathway (Systemic name M22017) and the IL-10/JAK/STAT signaling pathway that result in the repression of TNFα, IL-1, and IL-6 (Systemic name M6778)." (PMID 33256749, 2020). "PPARγ is an important regulatory factor during the differentiation process of pre-adipocytes, and its activation could accelerate adipocyte differentiation, thus aggravating obesity in patients." (PMID 33447177, 2020). "Similar to obesity, aged ATMs display an elevated expression of the chemokine receptor CCR2, possessed enhance secretion of pro-inflammatory cytokines IL-6, MCP-1, and TNFα, and a decrease in expression of PPARγ, which mechanistically accounts for the loss in M2 ATMs." (PMID 32499756, 2020). "Cardiac lipid overload caused by transgenic over-expression of peroxisome proliferator activated receptor gamma (PPARγ), without obesity or diabetes, causes spontaneous ventricular tachycardia and SCD with prolonged repolarization due to a decrease in Kv channel expression." (PMID 33086602, 2020). "Deletion of FABP4 increases PPARγ expression, and lipogenesis and insulin sensitivity in adipocytes, suggesting that FABP4-dependent inhibition of PPARγ might favor insulin resistance and induction of inflammatory pathways associated with obesity." (PMID 32856199, 2020). "Moreover, Pparγ is also known to be related to the regulation of the browning process, which may prevent obesity-related disorders." (PMID 30189642, 2018). "Therefore, activation of the β-catenin and PPARγ pathways in VAT-cDCs may serve not only to restrain obesity-induced inflammation, but also to promote pathogen persistence and tumor growth." (PMID 29514067, 2018). "Therefore, it is likely that the post-translational modification of PPARγ might affect VAT Treg cells in obesity." (PMID 30323806, 2018). "In this study, we report a novel role of TRIM25 in regulating metabolic pathways by mediating PPARγ ubiquitination and its proteasome-dependent degradation, suggesting that TRIM25 may be a potential therapeutic target in PPARγ-mediated metabolic diseases such as obesity and type 2 diabetes." (PMID 30323259, 2018). "In addition to lipid metabolism, PPARγ is involved in adipokine expression from adipose tissue, including adiponectin, a circulating plasma protein produced by white adipose tissue that negatively correlates with obesity." (PMID 30012954, 2018).
Obesity (continued). "Perhaps, in the future, the epigenetic modification of PPARγ may be intervened to regulate the expression of genes involved in lipogenesis without compromising metabolism in vivo, thereby reducing the occurrence of obesity and obesity-related diseases." (PMID 30034368, 2018). "We decided to base our GBR study on the PPARG Pro12Ala polymorphism due to its relatively high minor allele frequency, its strong association with influenced glucose disposal rates in the ULSAM study, and its well-characterized role in the context of obesity, insulin resistance, and type 2 diabetes." (PMID 29303622, 2017). "Additionally, 11β-HSDH1 knockout mice were demonstrated to be resistant to hyperglycemia caused by obesity and stress, and they were shown to have low resistin and TNF-α levels and high PPARγ and uncoupling protein 2 (UCP2) levels compared with these in the control." (PMID 28386270, 2017). "In summary, our study highlighted the significance of the additive effect of promoting thermogenic gene expression by a combination of PPARγ pathway and β3-Adrenergic pathway, which might be useful in developing a valid therapeutic implication for anti-obesity." (PMID 28481288, 2017). "Therefore, the anti-obesity effect of FSH may be attributed partially to suppression of PPARγ expression." (PMID 28248545, 2017). "Therefore, the aim of the research on the obesity-induced local chronic inflammation mechanism might be focused on the mediators PPARγ or NF-κB, potentially the key points for regulating inflammation." (PMID 28466023, 2017). "Therefore, investigation of PPARγ antagonists that may directly inhibit PPARγ activity by interrupting its functional pathway can be considered a logical approach for research in the fight against obesity." (PMID 27669202, 2016). "As we know, PPARG and the vitamin D system play conjunctly a yet-to-elucidate role in cancer, so it is not surprising at all that their hypothetical epigenetic repression in obesity could be another mechanism linking this metabolic disorder to malignancies." (PMID 27579030, 2016). "However, PPARγ activation may induce obesity and nonalcoholic fatty liver disease (NAFLD), one of the most challenging medical conditions." (PMID 26775807, 2016). "Therefore, additional studies of the PPARγ Pro12Ala polymorphism are necessary to fully elucidate the role of PPAR genetics in obesity independent of CVD, particularly with regard to available pharmacological PPAR-targeted agents." (PMID 28042289, 2016). "More recently, the anti-obesity effects of Lysimachia foenum-graecum (LFE) were associated with its ability to block adipogenesis in 3T3-L1 adipocytes through the possible link between LFE-induced activation of AMPK and AMPK-mediated suppression of PPARγ transcriptional activity." (PMID 27669202, 2016). "Thus, exercise-triggered adipocyte- and/or monocyte/macrophage-specific PPARγ activation may constitute an additional rationale for prescribing exercise in obesity and type 2 diabetes." (PMID 27379017, 2016). "Thus, the suppression of PPARγ transactivity may protect metabolic disorders such as obesity, fatty liver and insulin resistance." (PMID 26775807, 2016). "Therefore, moderate degrees of PPARγ blockade may provide better metabolic profiles by reducing obesity." (PMID 27176632, 2016). "Peroxisome proliferator-activated receptor gamma (Pparγ) participates in adipocyte differentiation, glucose and insulin homeostasis, and inflammation, and it was suggested that it plays an important role in several diseases, including obesity, diabetes, and atherosclerosis." (PMID 25802864, 2015). "PPARγ may therefore serve as an important molecular bridge between Twist 1 and obesity." (PMID 25128964, 2014). "Therefore, we may find an apparent reduction in circulating fetuin-A levels if we perform similar experiments in diabetic model mice because hepatic PPARγ expression is elevated in rodent models of diabetes or obesity." (PMID 24551137, 2014).
Obesity (continued). "Plasma levels of adiponectin are paradoxically reduced in obesity, the metabolic syndrome, T2DM and in the presence of CVD and increased in response to weight loss and thiazolidinedione (TZD)-induced peroxisome proliferator-activated receptor-gamma (PPAR-γ) activation." (PMID 29552090, 2014). "Interestingly, there is no general deficiency in PPARγ function in obesity or insulin-resistant states." (PMID 23431283, 2013). "Therefore, the use of pomegranate-derived compounds and fatty acids holds promise as prophylactic interventions for obesity and diabetes since some of them are PPARα and PPARγ activators that contribute to correct the abnormalities of lipid metabolism and regulate inflammatory responses." (PMID 23737845, 2013). "In this context, perturbation of adipocyte functions in obesity might be linked essentially to modified rather than deficient PPARγ transcriptional regulatory activities as discussed hereafter." (PMID 22991504, 2012). "However, the molecular basis of improved insulin sensitivity by activation of this “pro-obesogenic” receptor is incompletely understood, especially considering that obesity and T2D do not represent states of PPARγ deficiency." (PMID 22745632, 2012). "In obesity, these regulatory pathways may be altered and lead to modified PPARγ activity." (PMID 22991504, 2012). "The exception is the PPARG Pro12Ala/rs1801282 variant, which has not featured as a top-ranking variant in GWAS, but may be associated with obesity through interactions with lifestyle factors such as dietary fat intake." (PMID 24278702, 2012). "Other universal genes previously shown to be increased during the expansion of the β-cell during obesity or pregnancy such as Birc5, Igf1r and Rasgrp1 also failed to increase in PPARγ deficient ob/ob islets (POKO vs. WT) further suggesting an inability of POKO islets to proliferate at a young age." (PMID 22208362, 2011). "Given that PPARγ is necessary for the maturation of alternatively activated macrophages, and PPARγ is a transcription factor that regulates adipogenesis, insulin sensitization and inflammation, the potentiation of PPARγ-signalling would be beneficial in obesity." (PMID 20508722, 2010). "Thus, food components with PPARγ agonistic activities may also contribute to the improvement of obesity-induced inflammation via adipose tissue remodeling associated with the phenotype switch of macrophages." (PMID 20508825, 2010). "Dysfunction of BMAL1, CLOCK and PPARγ may lead to obesity and metabolic syndrome." (PMID 20706650, 2010). "Interestingly, macrophage-specific ablation of PPARγ resulted in high rates of insulin resistance suggesting that macrophage PPARγ may exert a protective role in obesity." (PMID 20871817, 2010). "Mice with genetic deletion of PPARγ in skeletal muscle showed significantly increased whole-body insulin resistance, demonstrated either by insulin/glucose tolerance tests or by hyperinsulinemic euglycemic clamp studies, and developed dyslipidaemia, enlarged fat pads, and obesity on high-fat diet." (PMID 20182551, 2009). "Various changes in the activity and expression of PPARγ in obesity have been reported, including a decrease in transcription and translation, activation of the degradation of both its mRNA and protein, and a decline of the ligand-binding affinity of PPARγ by post-translational modification." (PMID 19589179, 2009). "We have not found association of the PPARG selected polymorphism with obesity in this population." (PMID 18657264, 2008). "Furthermore, by inducing theexpression of adiponectin in adipocytes, PPARγ may directly contribute to suppression of chronic inflammationaccompanying obesity." (PMID 17389767, 2007). "Partial PPARγ agonists, such as FK614,that differentially activate PPARγ target genes may beeffective in treating metabolic disease while reducing the sideeffects (e.g., promoting obesity) caused by current TZD-basedtreatments." (PMID 17389765, 2007).
Obesity (continued). "At a time when the twin epidemics of obesity and type 2 diabetes threaten to engulf even the most well-resourced Western healthcare systems, the nuclear receptor peroxisome proliferator-activated receptor γ (PPARγ) has emerged as a bona fide therapeutic target for treating human metabolic disease." (PMID 17389771, 2007). "The serine 273 (Ser273) phosphorylation of PPARγ is regulated by cyclin-dependent kinase 5 (CDK5) and extracellular signal-regulated kinase (ERK) and is higher in mouse models of diet-induced obesity." (PMID 40985048, 2025). "External factors, such as cold exposure and β3-adrenergic receptor (β3-AR) agonists or peroxisome proliferator-activated receptor gamma (PPARγ) agonists, can induce WAT browning, leading to UCP1-dependent thermogenesis and increased resistance to obesity." (PMID 40369420, 2025). "Firstly, we detected expression levels of key adipogenesis genes, such as CEBPA, PPARG, lipoprotein lipase (LPL), fatty acid binding protein 4(FABP4) and perilipin 1 (PLIN1), which play critical roles in the development of obesity." (PMID 39773638, 2025). "Excessive intra-ovarian PPARG production within granulosa cells disrupts steroidogenesis and contributes to PCOS, obesity, and insulin resistance." (PMID 40328871, 2025). "The transcription factor PPARγ (Peroxisome Proliferator-Activated Receptor Gamma) for the LPL gene is regulated by insulin, and this regulation is significantly affected by obesity." (PMID 41373652, 2025). "While PPARγ activation promotes adipogenesis to buffer excess lipids, its sustained activation in HFD conditions exacerbates obesity-related inflammation and metabolic dysfunction." (PMID 40282189, 2025). "Recent studies have explored the effects of high-fat diets on gene expression in adipose tissue, revealing specific gene alterations that contribute to obesity and insulin resistance such as ADIPOQ, CD36, PPARG, and IL6." (PMID 40408066, 2025). "DNA methylation is closely related to the development of obesity by affecting gene expression, then disrupting the regulatory balance between obesity-promoting genes (such as FTO and PPARγ) and anti-obesity genes (such as LEP, GLP-1R, and POMC)." (PMID 39200098, 2024). "Additionally, capsaicin may suppress obesity by suppressing PPARγ signaling pathway." (PMID 38699583, 2024). "Taken together, our molecular dynamics results suggest that OA has binding stability to core targets, especially PPARG, PPARA, and PTGS2, which have very high potential in OA anti-obesity." (PMID 38246999, 2024). "We thus reveal a novel ACSS2 function in coupling PPARγ activation with degradation via SIRT1 and suggest D-mannose as a novel adipose plasticity regulator via ACSS2 to prevent obesity." (PMID 38332049, 2024). "On the contrary, deletion of PPARγ in POMC neurons in high-fat diet fed mice attenuated hyperphagia, increased energy expenditure, and protected from obesity and leptin resistance." (PMID 39290326, 2024). "Integration analysis using a skyline query revealed three main targets, EP300, PPARG, and PPARGC1A, which are potential targets for fighting obesity." (PMID 39208245, 2024). "Formononetin protected mice from diet-induced obesity and facilitated a higher level of energy expenditure through increasing UCP1 following binding to PPARγ." (PMID 39062047, 2024). "By inhibiting preadipocyte differentiation into mature adipocytes via suppression of PPARγ, the ability to expand WAT lipid storage in obesity is limited, contributing to ectopic lipid deposition and lipotoxicity." (PMID 39063184, 2024). "Additional animal studies confirmed the significance of the core target PPARG and the core pathway PPAR signaling pathway in OA anti-obesity." (PMID 38246999, 2024). "pTSL@(P+I) effectively upregulates UCP1 and COX5B expression by activating the transcription axis of PPARγ/PGC1α and HSF1/PGC1α, thereby promoting white adipose tissue browning and reducing obesity." (PMID 39195401, 2024).
Obesity (continued). "Upregulation of adiponectin and SIRT-1 expression after sleeve gastrectomy in a murine model of sequential HFD-induced obesity and streptozocin-induced T2DM resulted in browning of SAT via PPARγ, PGC-1α, and UCP1 activation." (PMID 39063184, 2024). "This study underscores the power of the 3DHFC-TRS algorithm in uncovering bioactive compounds from natural sources, such as thunder god vine, and highlights the therapeutic promise of PPARG and PTGS2 as novel obesity-related targets." (PMID 39684213, 2024). "The volcano plot also confirmed significant downregulation of various genes in inflammation and obesity including IL-6, IL-1B, CCL2, PPARg, and Fabp4." (PMID 38512816, 2024). "Adiponectin enhances cold-induced subcutaneous WAT (scWAT) browning and its genetic ablation showed impaired adaptive thermogenic program following cold exposure or high-fat diet -induced obesity in both scWAT and BAT, and PPARγ expression downregulation." (PMID 38987854, 2024). "Recently, peroxisome proliferator-activated receptor-gamma (PPAR-γ), the master regulator of adipogenesis, was discussed as a potential modulator of autophagy in obesity." (PMID 39421246, 2024). "The results of skyline query analysis showed that EP300, PPARG, and PPARGC1A were dominant and, therefore, have potential as targets for treating obesity." (PMID 39208245, 2024). "This suggests that PPARG, PPARA, and other targets should be the primary direct targets for OA to exert its anti-obesity effects." (PMID 38246999, 2024). "Furthermore, some studies have suggested that sodium valproate-induced obesity and weight gain might be linked to CD36 and PPARγ polymorphisms, with these genetic factors potentially serving as predictive markers for sodium valproate-induced obesity in Chinese Han epilepsy patients." (PMID 39121110, 2024). "This nanocomplex effectively upregulates UCP1 and COX5B expression by activating the transcription axis of PPARγ/PGC1α and HSF1/PGC1α, thereby promoting white adipose tissue browning and improving obesity." (PMID 39195401, 2024). "Obr is a target of Pparγ, which is active by HFD lipids, resulting in altered lipid metabolism and diet‐induced obesity." (PMID 38704700, 2024). "Suppression of the PI3K/Akt pathway and downregulation of PPARG by traditional herbal bioactive compounds may suppress adipogenesis, possibly leading to a reduction in adipocyte triglyceride and total cholesterol accumulation, which may ultimately prevent obesity." (PMID 39409084, 2024). "AMPK and PPARγ are the fundamental targets in metabolic disorders, including NAFLD, diabetes, osteoporosis, and obesity." (PMID 38534764, 2024). "During unhealthy obesity, the hypertrophic adipocytes are characterized by reduced PPARγ and CEBPa (this report and87) which indicates an inhibition of the adipogenesis in the WAT of morbidly patients with obesity undergoing bariatric surgery." (PMID 38677183, 2024). "These small molecules, due to their significant PPARG activation and PTGS2 inhibition, demonstrate novel application potential in obesity treatment." (PMID 39684213, 2024). "The animal experimental validation results also showed that the PPARG and PPAR signaling pathways are critical for the anti-obesity impact of OA on obese mice." (PMID 38246999, 2024). "As expected, Pparγ and C/ebpα expression levels were higher in subcutaneous, perirenal, and epididymal adipose tissues from mice with HFD-induced obesity than from mice fed a BD." (PMID 36820208, 2023). "The underlying theme of these studies suggests that the transcription factor PPARγ, a master regulator of adipogenesis, is the key pathophysiological link between BPA substitutes and obesity." (PMID 37529602, 2023). "The activated AMPK regulated the mRNA expression related to adipogenesis (PPARγ, C/EBPα, FABP4), lipogenesis (SREBP-1c, ACC, FAS), and lipolysis (ATGL, HSL) to inhibit obesity." (PMID 36678138, 2023).